CD28 (CD28 molecule)
Diseases named in the same sentence as CD28 in open-access papers (continued):
Sharing a sentence is not in itself a finding about the gene and the disease.
metastatic melanoma (5 papers, 2019 to 2024). A melanoma that has spread from its primary site to another anatomic site. "RNA-seq profiling of plasma EVs isolated from metastatic melanoma patients showed a decrease in several transcripts and pathways related to CD28 costimulatory, T-cell receptor, and CTLA4 signaling during treatment with ICIs in non-responders." (PMID 39336143, 2024). "However, a flow cytometry analysis of EVs collected from metastatic melanoma patients treated with an immunotherapeutic agent, the monoclonal antibody ipilimumab, showed, at baseline, that the levels of EV-PD1 and CD28 from T-cells were associated with improved PFS and overall survival." (PMID 39336143, 2024). "CD28 expression is improved on CD4+ and CD8+ T cell surrounding metastatic melanoma cells and in the expression of CD28 on T lymphocytes circulating in peripheral blood of patients suffering from metastatic breast cancer is associated with poor prognosis." (PMID 32902664, 2021).
tetanus (5 papers, 2016 to 2024). A serious infectious disorder that follows wound contamination by the Gram-positive bacterium Clostridium tetani. "Further functional characterization revealed defective T cell expansion following mitogenic stimulation by anti-CD3/CD28 antibodies, phytohemagglutinin (PHA), purified protein derivative (PPD), or tetanus antigens (TT) in 15 of 20 patients (75%)." (PMID 39776909, 2024). "Comparing antigen‐specific stimuli, tetanus, and dust mite proteins induced greater cytokine secretion than cockroach, while the polyclonal stimuli PHA and paired CD3+/CD28+ monoclonal antibodies induced the greatest cytokine secretion." (PMID 27042305, 2016). "T-cell proliferation to CD3/CD28 stimulation was normal in seven patients, missing for P4 and P9, who had normal T-cell proliferation to antigen stimulation (tetanus and diphtheria; data not shown)." (PMID 34080085, 2021).
Type 2 Diabetes (5 papers, 2015 to 2024). "In the context of diabetes mellitus, hASCs, from patients with type 2 diabetes (T2D), exhibited compromised antiproliferative potential on autologous anti-CD3/CD28-activated peripheral blood mononuclear cells (PBMCs)." (PMID 37962697, 2024). "A significant increase in T cell immunosenescence, as based on multiple markers (including naïve cell markers CD27/CD45RO, CD28, CD127 and CD57), is observed in type 2 diabetic patients with eGFR below 60 ml/min." (PMID 33088331, 2020).
AIDS (4 papers, 2008 to 2020). A syndrome resulting from the acquired deficiency of cellular immunity caused by the human immunodeficiency virus (HIV). "Notably, it has been shown previously that decreases in the absolute numbers of CD8+CD28+ T cells are predictive for progression to AIDS in HIV-1 infected individuals and associated with declining CD4+ T cell counts in SIV-infected SMs." (PMID 18636106, 2008). "Downregulation of CD28 has been previously reported to occur in lymphoid tissues of HIV-infected patients who progressed to AIDS." (PMID 22511950, 2012). "The predominance of HIV-specific cytotoxic T cells lacking CD28 expression is related with progression of the disease or AIDS development." (PMID 32187205, 2020). "However, other studies have suggested that CD28/HLA-DR expression on CD4+ T cells, but not on CD8+ T cells, is an important predictor for progression to AIDS." (PMID 32187205, 2020).
ankylosing spondylitis (4 papers, 2005 to 2021). An autoimmune chronic inflammatory disorder characterized by inflammation in the vertebral joints of the spine and sacroiliac joints. "In ankylosing spondylitis, TLR4 (23.1 ± 21.9%) and, to a smaller extent, TLR2 (4.1 ± 5.8%) were expressed on CD4+CD28null T cells, whereas expression was negligible on CD4+CD28+ and CD8+ T cells." (PMID 16277694, 2005). "In ankylosing spondylitis (AS), as in other immune-mediated diseases, an unusual proinflammatory and cytotoxic CD4+ T-cell subgroup has been described, which lacks the co-stimulatory molecule CD28." (PMID 16277694, 2005).
Anxiety (4 papers, 2016 to 2023). Intense feelings of nervousness, tension, or panic often arise in response to interpersonal stresses. "Meanwhile, CD4+CD27+CD28+ Th and Treg cells were significantly reduced in SLE patients with anxiety." (PMID 34955935, 2021). "Our findings indicated that the T cell subsets closely related to SLE (CD27+CD28+ Th/Treg, CD27−CD28− Th/Treg, CD45RA−CD27− Th, and CD45RA+HLADR+ Th) may be involved in SLE patients with anxiety." (PMID 34955935, 2021). "Furthermore, BMI, fatigue, depression, unstable emotions, CD27+CD28+ Th/Treg, CD27−CD28− Th/Treg, CD45RA−CD27− Th, and CD45RA+HLADR+ Th cells may be important characteristics between SLE patients with- and without-anxiety groups." (PMID 34955935, 2021).
B-cell acute lymphoblastic leukemia (4 papers, 2020 to 2024). A neoplasm of lymphoblasts committed to the B-cell lineage, typically composed of small to medium-sized blast cells. "Response and relapse outcomes in trials assessing CD19 CAR-T therapy with CD28/CD3ζ co-stimulatory domains in B-cell acute lymphoblastic leukemia with potential bridging to allogeneic hematopoietic cell transplantation." (PMID 33415078, 2020). "In relapsed or refractory B-cell acute lymphoblastic leukemia (r/r B-ALL), 4-1BB-based CAR-T cells have been shown to show higher antitumor efficacy, longer persistence, and fewer serious adverse events than CD28 CAR-T cells." (PMID 36761742, 2023). "In preclinical studies of CAR-T cells in pre-B cell acute lymphoblastic leukemia (pre-BALL) mice, compared with CD28 costimulation or CD3ζ signaling alone, 4-1BB costimulation of CAR-T cells improved the survival of tumor-bearing mice." (PMID 36761742, 2023).
breast tumors (4 papers, 2017 to 2024). "Finally, co-culture with breast tumor slides was found to substantially upregulate CCR8 mRNA in CD3/CD28-activated Tregs." (PMID 38231448, 2024).
Chagas disease (4 papers, 2013 to 2022). A parasitic infection caused by Trypanosoma cruzi. "Furthermore, in human Chagas disease higher percentages of CD28− T cells have been associated with increased IL-10 production." (PMID 23383358, 2013). "Through comparing the proportion of CD28 and CTLA-4 ligands in each lymphocyte subsets between patients with Chagas disease, we observed a higher proportion of CD28 on CD8+ Treg cells only after anti-CD80 blockade from CARD in comparison with anti-CD86 blockade and to IND group." (PMID 35665256, 2022). "Conversely, in other chronic or persistent infections such as schistosomiasis, Chagas’ disease, and HIV infection a decrease of CD28 expression is also found." (PMID 25148903, 2014). "In patients with Chagas disease, regardless of the clinical form, the same proportion of CD28 on Th1, Th2, Th17, and CD4+ Treg was observed in the three cultures of PBMC evaluated." (PMID 35665256, 2022).
Granuloma (4 papers, 2014 to 2021). A compact, organized collection of mature mononuclear phagocytes, which may be but is not necessarily accompanied by accessory features such as necrosis. "The granulomas consist of different cell types that are not influenced by the specific effect of costimulatory blockage of CD28-mediated T cell activation." (PMID 31950032, 2019).
Hepatic fibrosis (4 papers, 2019 to 2025). The presence of excessive fibrous connective tissue in the liver. "CD28 signalling in T Helper cells, Phospholipase C signalling and NF-κB signalling were upregulated in the chronic phase in sheep, but downregulated in cattle, while the hepatic fibrosis pathway was ineligible for prediction of activation/inhibition." (PMID 34616397, 2021). "The function of CD8 T cells from peripheral blood mononuclear cells (PBMCs) in CCl4‐treated mice was evaluated at peak liver fibrosis, by ex vivo stimulation with anti‐CD3 and anti‐CD28 antibodies for 48 h." (PMID 40760842, 2025). "Following anti-CD3/-CD28 stimulation, the proportion of perforin+ CD8+ T-cells cells from HCV+(F4) individuals with advanced liver fibrosis (mean 23.39%) was significantly greater than HCV+(F0-1) individuals (mean 9.44%) or healthy controls (mean 9.0%) (p = 0.02, ANOVA)." (PMID 31456810, 2019).
Hepatitis (4 papers, 2008 to 2024). Inflammation of the liver. "To illustrate the potential utility of restricted biomarkers, we compared the performance of CD27+ CD28+ CD4+ TEM frequency as a biomarker of hepatitis risk in our unrestricted and restricted datasets." (PMID 38926389, 2024). "Using our restriction method, we identified CD27+ CD28+ CD4+ TEM cell frequency relative to CD4+ in blood as a biomarker of hepatitis risk after dataset restriction." (PMID 38926389, 2024). "In addition, the mice with a targeted mutation of either B7 or CD28 had a reduced susceptibility to Con A induced hepatitis, which is known to be mediated by NKT cells." (PMID 18628995, 2008). "Accordingly, using the unrestricted dataset, CD27+ CD28+ CD4+ TEM (%) correctly predicted the incidence of hepatitis in 74 of 110 patients." (PMID 38926389, 2024). "The discriminatory cutoff for patient classification, defined by the Youden index, was the same for both the restricted and unrestricted datasets, such that samples with more than 9.56% of CD27+ CD28+ CD4+ TEM relative to CD4+ are predicted to be hepatitis positive." (PMID 38926389, 2024). "To confirm the immunosuppressive effects of MDSCs in ConA-induced hepatitis, we isolated the hepatic MDSCs from LXRα−/− and WT mice respectively and cocultured the MDSCs with T cells activated by anti-CD3/CD28 beads at different effector-and-target ratios." (PMID 34512667, 2021). "In univariate analyses, dataset restriction identified new biomarkers associated with ICI-related hepatitis, including CD27+ CD28+ CD4+ TEM cells, that were not returned by conventional methods." (PMID 38926389, 2024).
Hypertension (4 papers, 2019 to 2025). The presence of chronic increased pressure in the systemic arterial system. "Peripheral CD28+PD1−/CD8+ T cells were associated with stage, grade, and LVSI, inversely correlated with age, and reduced in patients with hypertension or dyslipidemia." (PMID 40136325, 2025). "Similarly, patients with dyslipidemia (44.46% vs. 36.93%, p = 0.023) and hypertension (46.47% vs. 37.43%, p = 0.008) had higher proportions of CD28−/CD8+ T cells in PBMC compared to patients with normal lipid levels or blood pressure." (PMID 40136325, 2025).
juvenile idiopathic arthritis (4 papers, 2013 to 2025). Juvenile idiopathic arthritis (JIA) is the term used to describe a group of inflammatory articular disorders of unknown cause that begin before the age of 16 and last over 6 weeks. "During follow-up, patients with juvenile idiopathic arthritis showed lower total counts of naive and CD28-expressing T cells compared to healthy donors." (PMID 23692985, 2013).
LGL leukemia (4 papers, 2016 to 2025). "A vast majority of patients (80%-90%) with T-LGL leukemia showed a CD3+ CD4-CD8+ CD57+ CD56- CD28-,TCRαβphenotype, while CD4- CD8- usually accompanied with TCR γδ, but had a favorable survival of 85% at 3 years." (PMID 28427176, 2017). "In approximately 80%–90% of T-LGL leukemia cases, the phenotype of CD3(+), CD8(+), CD57(+), CD56(−), CD28(−), and TCR-αβ(+) is observed." (PMID 40860493, 2025). "For example, TCR Vβ usage has been studied on CD3+, CD4+, and CD8+ T cells in LGL leukemia patients, or in naïve, effector, and memory lymphocytes in healthy subjects, or in total CD4+ and CD8+, effector CD4+CD28+ and CD8+CD28+, and effector memory CD4+CD28−CD57+ and CD8+CD28−CD57+ cells in AA." (PMID 34572739, 2021). "Most LGL leukemias (80–90%) are CD3 positive with co-expression of CD8, CD16 and CD57, with CD56 and CD28 being negative." (PMID 27047646, 2016).
liver disease (4 papers, 2017 to 2025). "However, persistent antigen stimulation resulting from chronic hepatitis and liver diseases may lead to continuous activation of CD28 and PD-1 signaling, resulting in an antigen tolerance response in HCC." (PMID 40534863, 2025). "Cyclopamine treatment (50 μM) of CD8 T cells alongside anti-CD3/CD28 stimulation ablated IFN-γ expression in bulk CD8 T cells regardless of liver disease severity, in a dose-dependent manner." (PMID 38887299, 2024). "Compared with patients without cirrhosis, the expression of CD28 was reported to be reduced in those with cirrhosis and portal hypertension." (PMID 28282876, 2017).
lymph node metastasis (4 papers, 2012 to 2024). "The baseline pTCD8+CD28- level exhibited a significant negative correlation with bone metastasis (coefficient = −0.189, P = 0.003), lymph node metastasis (coefficient = −0.152, P = 0.016), and the number of metastatic sites (coefficient = −0.200, P = 0.001)." (PMID 38519706, 2024).
Parkinson disease (4 papers, 2016 to 2025). A progressive degenerative disorder of the central nervous system characterized by loss of dopamine producing neurons in the substantia nigra and the presence of Lewy bodies in the substantia nigra and locus coeruleus. "In mouse models of Parkinson’s disease, treatment with Cd28 agonists has been shown to significantly increase Tregs and mitigate early-stage degeneration of nigrostriatal dopaminergic neurons." (PMID 40072375, 2025). "We found that PD patients exhibited decreased naïve CD8+ T cells (CD3+ CD8+ CD45RA+ CD45RO−) and increased late-differentiated CD4+ T cells (CD3+ CD4+ CD28− CD27−), compared to HC, which were not affected by anti-parkinsonism medication administration." (PMID 35608657, 2022).
Pleural effusion (4 papers, 2017 to 2025). The presence of an excessive amount of fluid in the pleural cavity. "We evaluated the capacity of CD8+ T cells from the pleural effusion sample to secrete IFN-γ and GZMB following 3 days of CD3/CD28 stimulation." (PMID 40040705, 2025). "When injected into the pleural effusion of a patient with malignant pleural mesothelioma (MPM), the Δ‐CD28 CAR could be detected for up to 21 days and exhibited functionality." (PMID 40656546, 2025). "However, there was an elevated population of memory (CD45RA−CD45RO+CD27+CD28+) CD8+ T cells and a low proportion of terminally differentiated (CD45RA+CD45RO−CD27−CD28−) CD8+ T cells in the pleural effusions." (PMID 28101811, 2017).
preeclampsia (4 papers, 2019 to 2022). Preeclampsia is a hypertensive disorder of pregnancy that is characterized by new-onset hypertension with proteinuria presenting after 20 weeks of gestation, and depending on mild or severe forms may initially present with severe headache, visual disturbances, and hyperreflexia. "When preeclampsia was alleviated with CD28 monoclonal antibody treatment (JJ316) in rat preeclampsia model, the number of Tregs in peripheral blood and the weight of foetal rats were increased." (PMID 32057179, 2020). "Substantial promise for a CD28 superagonist treatment was demonstrated in a rat model of preeclampsia induced by overexpression of human angiotensinogen." (PMID 30984163, 2019). "In preeclampsia, CD8+ CM cell proportions and their CD28 and CD27 expression were comparable to the proportions in healthy women, both in peripheral blood and in a swab from the intrauterine cavity." (PMID 31001255, 2019). "In preeclampsia, CD8+ EM cell proportions and their CD27 and CD28 expression were comparable to CD8+ EM cell proportions in healthy women in peripheral blood and in a swab from the intrauterine cavity." (PMID 31001255, 2019). "Another study utilizing another group of multiple preeclampsia gene sets showed mainly immune-related genes (bone morphogenetic protein 5 (BMP5), cell surface glycoprotein (CD) 200R1 (CD200R1) and 28 (CD28), and TLR7) that are differentially expressed in preeclampsia." (PMID 35269385, 2022).
squamous cell carcinoma (4 papers, 2021 to 2025). A carcinoma arising from squamous epithelial cells. "DDR-deficient types had lower expressions of STING1 (p = 0.01), CD28 (p = 0.020), HLA-DRB6 (p = 0.014) in adenocarcinoma, lower TNFRSF4 (p = 0.017), and TGFB1 expressions (p = 0.033) in squamous carcinoma, and higher CD40 (p = 0.012) and TNFRSF14 expressions (p = 0.022) in SCLC." (PMID 34604048, 2021).
abscess (3 papers, 2009 to 2024). An inflammatory process characterized by the accumulation of pus within a newly formed tissue cavity which is the result of a bacterial, fungal, or parasitic infection or the presence of a foreign body. "It was proved that T cell activation by APCs through the CD28-B7 interaction is crucial for abscess formation as well as that the signalling through CTLA-4 (which is a cellular antagonist of CD28)-B7 inhibits abscess formation." (PMID 38397099, 2024). "Our results are also consistent with earlier reports suggesting an important role for CD28 in regulating abdominal abscess formation in CLP as well as the role for CD28 in mediating toxic shock in mice." (PMID 19672303, 2009). "First, we examined the effect of CD8+CD28− T cells on ZPS-induced abscess formation." (PMID 19779562, 2009). "In contrast, mSp1 without the positive charged substituent and therefore resembling a common negatively charged polysaccharide not only fails to induce CD4+ T cell-dependent abscesses but also CD8+CD28− T cells in the peritoneum and in the spleen." (PMID 19779562, 2009). "In contrast to the adoptive transfer of Sp1-induced CD8+CD28+ T cells that together cause intraperitoneal abscesses with a median abscess size of 4 mm, transfer of Sp1-induced CD8+CD28− T lymphocytes significantly inhibited the abscess formation (no abscess detected)." (PMID 19779562, 2009).
allergic asthma (3 papers, 2005 to 2011). A asthma with a basis in a pathological type I hypersensitivity reaction. "The finding that the MAPKs inhibitors very effectively inhibited several cytokines in CD4+ T cells costimulated through CD28 and ICOS, prompted us to investigate whether these selective MAPKs inhibitors may be active in an animal model of allergic asthma." (PMID 15833106, 2005).
ANCA-associated vasculitis (3 papers, 2017 to 2023). "In ANCA-associated vasculitis, CD28 was found to be downregulated on circulating and lesional CD4+ T- cells and CD4+CD28- T-cells have been described as the major source of pro-inflammatory cytokines (particularly IFN-γ and TNF-α) in Wegener’s Granulomatosis." (PMID 28991896, 2017). "Further, mechanistic studies in ANCA-associated vasculitis identified CD28null T cells acting independently of the CD28/CD80 pathway, which may explain why CD80/CD86 inhibition in ANCA disease may not be optimal." (PMID 36598752, 2023).
Ascites (3 papers, 2019 to 2025). Accumulation of fluid in the peritoneal cavity (between the layers of the peritoneum that lines the abdomen). "Human peripheral blood CD4+ and CD8+ T-cells were stimulated with anti-CD3/CD28-coupled beads and incubated with EVs isolated from 44 OvCa patients’ ascites." (PMID 31278254, 2019). "From a global perspective, SHAP importance rankings placed two immune features in the top five: PD-1+CD8+ T cells (0.268) and PD-1+CD28+CD4+ T cells (0.264)-outperforming ascites volume (0.250) and far exceeding the modest importance of surgical method (0.021)." (PMID 41479903, 2025). "Markers of immunosenescence in that study were increased in cirrhosis patients compared to healthy controls (i.e., higher proportion of CD8 + CD45RO + CD57+ T-cells) and in cirrhotic patients with ascites compared to healthy controls (i.e., lower proportion of CD28+ T-cells)." (PMID 31892306, 2019).